IL6 (interleukin 6)
Diseases named in the same sentence as IL6 in open-access papers (continued):
Sharing a sentence is not in itself a finding about the gene and the disease.
Cognitive impairment (continued). "One research found that T2DM patients with cognitive impairment had considerably greater peripheral blood IL-6 levels than T2DM patients without cognitive impairment, whereas another reported that T2DM patients’ IL-6 levels were significantly lower than those of healthy people." (PMID 37113152, 2023). "In our data, serum SOD levels were significantly lower in patients with cognitive impairment in the early phase and at 3 months after mild AIS than in those without cognitive impairment, accompanied by increased systemic inflammation biomarkers (ESR, CRP, and IL-6)." (PMID 35296032, 2022). "In addition, high TNF-α (P<0.001, adjusted P <0.001), IL-1β (P=0.033, adjusted P=0.132), and IL-6 (P=0.012, adjusted P=0.048), but not IL-17 (P=0.554, P=1.000 after adjustment) were correlated with cognition impairment occurrence." (PMID 35239774, 2022). "Systemic administration of IL-6 antibodies suppressed I/R-induced IL-6 elevations (P < 0.05), microglial reactivations (P < 0.05), IDO-1 expressions (P < 0.01), and neuroactive metabolite QUIN productions (P < 0.05) in the BLA, resulting in a recovery of cognitive deficits (P < 0.05)." (PMID 36160165, 2022). "Moreover, systemic inflammatory markers (ESR and IL-6) were significantly higher in patients with CI-L at baseline and follow-up periods than in those without cognitive impairment (nCI-L." (PMID 35296032, 2022). "We previously addressed IL-6 and TNF-’s many neurotoxic actions, which, when coupled with other neurotoxic substances like LPS and lipid peroxidation, may produce neurotoxicity and, hence, explain the cognitive deficits and phenome of schizophrenia." (PMID 36256663, 2022). "In addition, AASWE improved learning and memory function of LPS-induced cognitive deficits with the inhibition of oxidative stress, activation of the cholinergic system and regulation of pro-inflammatory mediators (p-JNK, p-NF-κB, TNF-α, and IL-6)." (PMID 33046678, 2021). "The exited tau could “swim” and travel into microglia with the assistance of EVs or non-EVs pathway, leading to generation of IL-6 and cognitive impairment." (PMID 33980987, 2021). "This is important as our findings do not corroborate the major hypothesis that IL-6 and other cytokines, which may induce pain, mental, and cognitive impairments, are increased in that illness." (PMID 31470635, 2019). "However, molecular mechanisms by which IL-6 overexpression lead to cognitive impairment have not been fully elucidated." (PMID 31129771, 2019). "First, the exclusion of participants with dementia or significant cognitive impairment, and those without functional limitation and/or IL-6, may yield a biased sample, reducing the generalizability of the findings." (PMID 30352583, 2018). "Several biomarkers were also highlighted as potential biomarkers of GDM-related cognitive impairment such as AGEs, serine-phosphorylated IRS-1 and inflammatory markers such as tumor necrosis factor α (TNF-α), high-sensitivity C-reactive protein (hs-CRP), leptin, interleukin 1β (IL-1β), and IL-6." (PMID 30563117, 2018). "Conversely, production of IL-6 has been shown to be necessary and sufficient for NOX2 increase in the ketamine model of schizophrenia, as well as the degeneration of forebrain GABAergic interneurons, along with cognitive impairment in aged mice, through activation of the neuronal NADPH oxidase." (PMID 26910819, 2017). "However, the highly toxic effect of IL-6 may overweight the potential compensatory effect of TNF-α and INF-γ, leading to cognitive impairment eventually." (PMID 24884485, 2014). "They concluded that IL-6, although not useful alone, has potential, in combination with other biomarkers, to support early diagnosis of amnestic MCI, because of its association with the progression of cognitive impairment." (PMID 23857873, 2014). "However, lidocaine attenuated isoflurane-induced cognitive impairment but did not change the isoflurane-induced increase of IL-6." (PMID 23251531, 2012).
Cognitive impairment (continued). "IL-6 was chosen due to its essential role in mediating the MIA response, but future studies may benefit from exploring additional inflammatory markers such as IL-1β and TNF-α to provide a more comprehensive picture of immune dysfunction in MIA-induced cognitive deficits." (PMID 40419496, 2025). "And laser acupuncture at DU20 could attenuate cognitive impairment and motor deficits in rats with ischemic stroke, whose specific mechanism may be attributed to increased neuronal survival in CA1 and CA3, increased GSH-Px and SOD activity, and decreased IL-6 to β-actin density ratio." (PMID 35449821, 2022). "Our findings suggest a potential role of IL-6 in the interplay between neuroinflammation and BACE1 levels, although this pathway was not to be altered in SS cognitive impairment." (PMID 40748886, 2025). "A cohort study illustrated that biomarker of neuroinflammation in the CSF such as IL‐6, IL‐15 and MCP‐1 are increased in AD patients with cognitive impairment compared to AD without cognitive impairment." (PMID 39644152, 2024). "Although HFFD did not lead to cognitive impairment in the present study, DI values were positively correlated with brain IL‐10 and negatively correlated with plasma CD36 and IL‐6." (PMID 39619979, 2024). "In fact, in one experiment, drebrin levels in the superior temporal cortex were found to be approximately 35% lower in subjects with mild cognitive impairment, who exhibited upregulation of TNF-α and IL-6, than in subjects without cognitive impairment." (PMID 36550479, 2022). "In summary, the negative correlation of FC with the level of IL-6, TNF-alpha and ammonia strengthens the role of systemic inflammation and hyperammonemia in the pathogenesis of cognitive impairment among cirrhotic patients with CHE55." (PMID 31036843, 2019). "Positive correlations observed between elevated IL-6 levels, as a key interleukin in the inflammation process and BACE1, suggest a potential relationship between inflammation and BACE1, although this pathway was not altered in SS cognitive impairment." (PMID 40748886, 2025). "Among others, IL-15, CX3CL1 and IL-6 were elevated in patients with minimal HE38, a cognitive impairment we did not assess, but which is likely present in our groups, and the markers could be correlated with both HE and death." (PMID 37973887, 2023).
melanoma (561 papers, 1993 to 2026). A malignant, usually aggressive tumor composed of atypical, neoplastic melanocytes. "Several circulating cytokines-most consistently interleukin-6 (IL-6) and interleukin-8 (IL-8)-are associated with adverse outcomes in advanced melanoma." (PMID 42195213, 2026). "Melanoma-derived exosomes activate tumor-associated fibroblasts (TAFs), inducing IL-6 and IL-8 secretion, reinforcing a pro-inflammatory phenotype that supports tumor progression." (PMID 41465101, 2025). "When IL-6 and IL-8 are deficient in the environment, the invasiveness of melanoma cells is suppressed." (PMID 41009413, 2025). "Clinically, elevated IL-6 levels have been associated with the occurrence of psoriatic dermatitis in patients with malignant melanoma receiving nivolumab therapy." (PMID 40519900, 2025). "Two studies have reported that lower baseline serum IL-6 levels were associated with the development of irAEs in melanoma patients treated with anti-CTLA-4 therapy." (PMID 40632185, 2025). "Sex differences indicated that females with melanoma had higher rates of irAEs, while increased baseline IL-6 levels were associated with colitis-related irAEs." (PMID 41239350, 2025). "For example, the IL6 induced STAT3 pathway is linked to an EMT signature in melanoma and its activation reduced the cell cycle as well as the differentiation associated pigmentation pathway." (PMID 38902533, 2024). "-Influences IL-1β, IL-6, and IL-33 plasma levels.-Protective against sporadic malignant melanoma.-Increased susceptibility to Mycobacterium tuberculosis infection in HIV-positive patients." (PMID 38920661, 2024). "Data for this study were obtained from the IEU Open GWAS project website for genome-wide association study data (GWAS) on interleukin-6, C reactive protein levels and malignant melanoma." (PMID 38952546, 2024). "In melanoma, elevated levels of IL-6 and TNF-α have been associated with increased tumor growth and poor prognosis." (PMID 39200315, 2024). "This is the case of BRAF mutations in melanoma cells correlating with enhanced levels of immunosuppressive mediators such as IL-6 and IL-10 or anti-apoptotic Bcl-2 and Bcl-xL proteins, regulating the expression of several interleukins, such as IL-8 and IL-1β." (PMID 36768978, 2023). "This would explain why SK-MEL-28-RhS, despite secreting considerable levels of TGFβ, did not induce contractility and is in line with the association of IL-6 and IL-8 with melanoma progression and metastasis." (PMID 37345186, 2023). "Of notice, both primitive and acquired resistance to targeted therapy have been associated with an increased capability of melanoma cells to produce both IL-6 and IL-10." (PMID 36765891, 2023). "Along with Breslow thickness, infiltrating L-BCL2+, and serum IL-4, IL-6 and GM-CSF levels appear to be relevant risk factors for melanoma progression." (PMID 37046835, 2023). "Along with the Breslow thickness, the Melanoma CDSS includes features such as the relative number of tumors infiltrating L-BCL2+ and serum levels of IL-4 or IL-6, all of which have been reported to be important risk factors for melanoma progression." (PMID 37046835, 2023). "On the other hand, mutated melanomas are enriched in IL-6, which has been shown to promote IL-17 secretion by ILC3s." (PMID 36765891, 2023). "It has also been shown that the high baseline serum IL-6 levels of melanoma patients were associated with poor response after nivolumab or ipilimumab treatment." (PMID 35205631, 2022). "This approach is based on the observation that BRAF-mutated melanoma cells have a low T cell infiltration and a high level of IL-6, IL-10, and VEGF, which increase the number of Tregs or myeloid-derived suppressor cells within TME." (PMID 35334544, 2022). "In fact, high secretion of IL‐6 has been associated with increased invasive migration in BRAF inhibitor‐resistant melanoma." (PMID 36176603, 2022).
melanoma (continued). "Interleukin-6 (IL-6), an acute phase reactant, is a deleterious prognostic marker for melanoma, as increased levels are associated with decreased survival in patients with this disease." (PMID 36081549, 2022). "Melanoma susceptibility to immunotherapies is reduced by CAFs production of IL6 and induction of IL10 in melanoma cells, the latter inhibiting antigen-presenting cells and weakening the immune response." (PMID 35558554, 2022). "Here, overexpression of α-SMA, IL-6, and IL-8 is the most prominent characteristic of melanoma-associated fibroblasts, suggesting the possible concomitant expression of these markers." (PMID 34298873, 2021). "Valpione and colleagues reported that a lower level of baseline circulating IL-6 was associated with increased irAE occurrence in melanoma patients treated with ipilimumab." (PMID 34732257, 2021). "Higher levels of IL-6 were detected in some melanoma patients treated with anti-PD-1, which was also associated with a worse prognosis." (PMID 34681685, 2021). "In melanoma patients, increased systemic levels of IL-6 were associated with poor clinical response." (PMID 33646368, 2021). "In a study of patients with stage IV melanoma, higher plasma concentrations of either IL-6 or IL-8, or both, were associated with worse survival." (PMID 33827575, 2021). "Serological analysis of CyKs, CKs, and GFs from malignant melanoma patients indicated a direct association between the levels of IL-6, IL-8, IL-13, VEGF and the values of the tumor thickness." (PMID 35011682, 2021). "A rise of serum IL-6 levels was associated with immune-related adverse events as well as with release of tumor marker in the majority of the treated melanoma patients presented in this study." (PMID 32188047, 2020). "HDFs expressing high levels of ATF3 suppressed the growth and migration of melanoma cells in association with downregulation of different cytokines including IL-6 in vitro." (PMID 32373541, 2020). "A therapeutic melanoma vaccine (AGI-101H) transduced with a fusion protein consisting of soluble IL-6 receptor and IL-6 linked by a flexible peptide chain was used in the adjuvant setting in melanoma patients." (PMID 32512674, 2020). "Melanoma cultures from this patient (patient 7) were shown to produce high levels of a range of cytokines including IL‐1β, IL‐6, IL‐8, and VEGF, which were associated with constitutive activation of NF‐kB." (PMID 32027447, 2020). "For instance, the level of baseline circulating IL6 and being female are associated with higher incidences of irAEs in ipilimumab-treated advanced-melanoma patients." (PMID 31816940, 2019). "This clinical study evaluated the association and impact of IL-6, IL-8, and circulating MDSCs on the long-term outcomes in melanoma patients." (PMID 31781510, 2019). "In the present study, we have shown for the first time that the development of acquired resistance to BRAFi causes a significant increase in IL‐6 secretion in BRAF‐mutant melanoma cells." (PMID 30582770, 2019). "Several previous studies have shown that IL-6 and IL-8 are associated with melanoma progression and metastasis." (PMID 31781510, 2019). "In a previous study, higher serum IL-6 was associated with shorter OS in melanoma patients treated with IL-2-based immunotherapy." (PMID 31192215, 2019). "Similar to the correlation with poor tumor response, it has been reported that circulating IL-6 at baseline was negatively associated with irAE occurrence in melanoma patients treated with ipilimumab." (PMID 31192215, 2019). "When BRAFi‐R melanoma cells were exposed separately to either an IL‐6 Ab or the WNT5A antagonist Box5, it caused, in both cases, impaired invasive migration of these cells." (PMID 30582770, 2019). "Here, we demonstrated for the first time that high secretion of interleukin‐6 (IL‐6) was associated with increased invasive migration of BRAFi‐R melanoma cells." (PMID 30582770, 2019).
melanoma (continued). "IL-6 is secreted by malignant melanoma cells, and the serum level is associated with advanced stages of the disease." (PMID 29219852, 2017). "Many of these canonical NF-κB target genes, including IL-1β, IL-6 and IL-8, have been associated with melanoma tumorigenicity, metastasis and angiogenesis, and represent potential targets for therapy." (PMID 27203220, 2016). "It was described that the integrin-linked kinase ILK, which correlates with melanoma progression and invasion, enhances the activity of NF-κB and thereby leads to the secretion of IL-6 and VEGF in melanoma cells." (PMID 26000250, 2015). "Specifically, low A-SMase in melanoma accounts for the high expression of factors involved in inflammation (i.e., IL-1β, IL-6, GM-CSF, and TNF-α), which have been positively associated with cancer onset and progression." (PMID 26101462, 2015). "Previously we reported, in metastatic B16-F10 melanoma-bearing mice, that tumor IL-6 silencing causes a significant decrease in circulating IL-6 and in hepatic GSH efflux, and consequently an increase in liver GSH content." (PMID 23517603, 2013). "Moreover, other published data showed that IL-6 is overexpressed in the resistant phenotypes of melanoma, the high levels being associated with shorter overall survival in patients receiving ICIs." (PMID 40564098, 2025). "Adipocyte-derived TNF-α and IL-6 are positively associated with PD-L1 expression in melanoma." (PMID 40399946, 2025). "As IL6 is mainly an acute inflammatory cytokine, presumably, an IL6 inhibitor may be used to treat the acute inflammatory responses caused by ICIs in melanoma patients that later exacerbate the autoimmune phenotypes." (PMID 39408929, 2024). "Interleukin-6 (IL-6) is a pro-inflammatory cytokine involved in the immune response, and high serum IL-6 levels have been linked to poor outcomes in melanoma patients treated with ICIs, likely due to its role in promoting an immunosuppressive tumor microenvironment." (PMID 39282490, 2024). "For example, high levels of IL-6, a typical inflammatory cytokine, are considered a risk factor for irAE, and tocilizumab, an anti-IL-6 receptor monoclonal antibody, can reportedly prevent irAEs in patients with melanoma undergoing ICI therapy." (PMID 38026978, 2023). "Interestingly, plasma IL-6 was associated prognostically with reduced survival of ICI-treated melanoma patients." (PMID 36599350, 2023). "Indeed, circulating cytokines in patient plasma such as interleukin-6 (IL-6), IL-8, and IL-10 were implicated in poor patient responses to ICBs in patients with kidney, breast, and bladder cancer and melanoma." (PMID 38259453, 2023). "Indeed, high serum levels of CXCL8 and IL-6 in melanoma have been associated with melanoma progression, higher tumor burden, and shorten PFS and OS in patients treated with biochemotherapy, Ipilimumab and Nivolumab." (PMID 35173725, 2022). "In addition, IL-6 and IL-8 are linked with MDSCs accumulation and correlate with poor clinical outcomes in melanoma patients." (PMID 36263056, 2022). "Since OSM is an interleukin-6 (IL-6) type cytokine to inhibit melanoma proliferation, the loss of OSM gene expression in drug-resistant patients may inhibit the activity of collagen biosynthesis and interleukin-6 family signaling." (PMID 35495152, 2022). "Cancer-associated fibroblasts were activated by the melanoma cell-produced exosomes significantly more than their normal counterparts, as assessed by increased transcription of genes for inflammation-supporting cytokines and chemokines, namely IL-6 or IL-8." (PMID 34837514, 2022). "Another study has emphasized that circulating B lymphocytes produce tumour necrosis factor α (TNF-α) and/or IL-6, these being associated with tumour unresponsiveness and poor survival of melanoma patients who underwent anti-cytotoxic T-lymphocyte associated protein 4 (CTLA4) antibody therapy." (PMID 35334544, 2022).